NUP107 (nucleoporin 107)
Diseases named in the same sentence as NUP107 in open-access papers:
NUP107 is named in the same sentence as 51 diseases in open-access papers, as found by Europe PMC text mining. Sharing a sentence is not in itself a finding about the gene and the disease. The quoted sentences say what the papers report.
glioblastoma (7 papers, 2017 to 2025). The most malignant astrocytic tumor (WHO grade IV). "Among these, Nup107 is identified as a potent oncogene in GBM (glioblastoma)." (PMID 39459201, 2024). "Consistent with our previous findings, the expressions of NUP107, DRAM1, RNF19A, PXDN, HEY2, F2R, and BMP2 were up-regulated in gliomas (glioblastoma multiforme + lower grade glioma)." (PMID 36245971, 2022).
microcephaly (5 papers, 2019 to 2023). A congenital or acquired developmental disorder in which the circumference of the head is smaller than normal for the person's age and sex. "Additionally, the loss-of-function variant in NUP133—the direct binding partner of NUP107—leads to Galloway–Mowat syndrome, which is characterized by microcephaly associated with early onset nephrotic syndrome and hiatus hernia." (PMID 36831309, 2023). "Interestingly, NUP107, another member of the NUP107-160 subcomplex, was also found to be mutated in a microcephaly form associated with nephrotic syndrome, which is similar to the Galloway–Mowat syndrome." (PMID 31878213, 2019). "Notably, the study revealed that the NUP107 c.303G>A (p.Met101Ile) mutation was recurrent, as it has been identified in five families with the combined phenotype, SRNS–microcephaly and ID." (PMID 38136965, 2023).
nephrotic syndrome (4 papers, 2019 to 2024). A collection of symptoms that include severe edema, proteinuria, and hypoalbuminemia; it is indicative of renal dysfunction. "NUP85 is related to the composition of the Nup107–160 subunit of the nuclear pore complex, mostly associated with nephrotic syndrome." (PMID 36452490, 2022). "In particular, previous genetic studies of patients with nephrotic syndrome identified mutations in Nup107 that impaired the expression or the localization of its direct partner at nuclear pores, Nup133." (PMID 30894603, 2019).
cervical cancer (3 papers, 2022 to 2025). A primary or metastatic malignant neoplasm involving the cervix. "NPC formation is closely associated with tumorogenesis and NUP107-160 members, particularly NUP88 and NUP107, have been shown to promote the survival and invasion of cervical cancer cells." (PMID 41153808, 2025). "Several studies have demonstrated the overexpression of NUP107 in cervical cancer, colon cancer, lung cancer, and other tumors, although little is known regarding its role in liver cancer." (PMID 36952458, 2023). "In addition, NUP88 is a novel cancer biomarker that is closely related to tumor progression and invasion, while NUP107 promotes survival of cervical cancer cells." (PMID 36952458, 2023). "In addition, NUP107 can also improve the ability of cervical cancer cells to resist oxidative damage." (PMID 36952458, 2023). "Besides, overexpression of NUP107 promotes the sensitivity of cervical cancer cells to oxidative insults." (PMID 35416526, 2022).
hepatocellular carcinoma (3 papers, 2023 to 2024). A malignant tumor that arises from hepatocytes. "Gene expression analysis of patient samples from the liver hepatocellular carcinoma dataset in The Cancer Genome Atlas revealed a positive correlation between high expression of NUP107–160 complex components, including AHCTF1, and worse overall survival in HCC patients." (PMID 39000572, 2024).
breast carcinoma (2 papers, 2012 to 2017). "Six of the 11 non-mitosis related genes were previously associated with poor survival in breast cancer patients: KRT17, MMP12, SLC7A5, SQLE, GABRP and PA2G4, but the remaining 5 had not been previously associated with cancer risk: CCDC86, NUP107, NUTF2, WASF1 and ELOVL6." (PMID 23077491, 2012).
gastric cancer (2 papers, 2021 to 2022). A primary or metastatic malignant neoplasm involving the stomach. "qRT-PCR verified that ZFPM2-AS, NUP107 and C8orf76 were highly expressed in gastric cancer cells." (PMID 35416526, 2022).
HIV-1 infection (2 papers, 2018 to 2024). The type species of lentivirus and the etiologic agent of acquired immunodeficiency syndrome (AIDS). "Moreover, some Nup depletions (SEH1, NUP85, NUP160, SEC13, NUP98, NUP107, ELYS/ACHTF1, NUP93, NUP205, NUP88, and NUP214) that reduced both HIV-1 infection and MX2 activity in dividing HeLa cells, affected MX2 activity but not HIV-1 infection in non-dividing HeLa cells." (PMID 30084827, 2018).
Infertility (2 papers, 2018 to 2022). "Our findings indicate that NUP107 R355C variant falls in the category of variant of unknown significance as the cause of HH and infertility." (PMID 29363275, 2018). "We previously found that Nup107 mutant female flies with normal-sized ovaries suffered from infertility due to defective oogenesis." (PMID 35311642, 2022).
non-small cell lung carcinoma (2 papers, 2017 to 2023). A group of at least three distinct histological types of lung cancer, including non-small cell squamous cell carcinoma, adenocarcinoma, and large cell carcinoma. "In non-small cell lung cancer, NUP107 overexpression has also been previously reported, and another nucleoporin family member, NUP37, was found responsible for increased cell proliferation in vitro." (PMID 37345045, 2023).
ovarian carcinoma (2 papers, 2022 to 2023). A malignant neoplasm originating from the surface ovarian epithelium. "Interestingly, a variant in NUP107 has been reported to be significantly associated with resistance to chemotherapy in ovarian cancer." (PMID 37345045, 2023).
Primary amenorrhea (2 papers, 2018 to 2022). "Here we report a new NUP107 (c.1063C>T, p.R355C) variant, discovered in two sisters who were diagnosed with primary amenorrhea and HH." (PMID 29363275, 2018). "We identified a NUP107 genetic variant in a nonconsanguineous family with two sisters affected with primary amenorrhea and HH, and generated a mouse model that carried the human variant." (PMID 29363275, 2018).
acute myocardial infarction (1 paper, 2019). Necrosis of the myocardium, as a result of interruption of the blood supply to the area. "Furthermore, we examined the expression of Nup107 and Nav1.5 in a rat model of acute myocardial infarction." (PMID 30506890, 2019).
Autoimmunity (1 paper, 2017). The occurrence of an immune reaction against the organism's own cells or tissues. "For example, in the largest subunit of the NPC, 3 out of 9 putative complex members of the Nup107-160 sub-complex, i.e., MOS3/Nup96, Nup160, and Seh1, were found to be essential for the basal resistance and snc1 activated autoimmunity in Arabidopsis." (PMID 28205154, 2017).
cardiac arrhythmia (1 paper, 2019). Any disturbances of the normal rhythmic beating of the heart or MYOCARDIAL CONTRACTION. "Considering that Nup107 mRNA was significantly increased 3 days after myocardial infarction, when is concomitant with the susceptible period of cardiac arrhythmia, we attempted to explore the potential roles of Nup107 in the regulation of ion channel expression." (PMID 30506890, 2019).
cervical tumors (1 paper, 2023). "Overexpression of NUP107 in cervical tumors has been reported, and it confers a pro-survival advantage through resistance to oxidative damage that can be reversed by silencing NUP107." (PMID 37345045, 2023).
congenital heart disease (1 paper, 2024). A heart disease that is present at birth. "Previous studies have linked NUP93, NUP107 and NUP160 to cancer, congenital heart disease, neurological diseases and gonadal dysgenesis." (PMID 38650033, 2024).
esophageal squamous cell carcinoma (1 paper, 2021). Esophageal squamous cell carcinoma (ESCC) is a type of esophageal carcinoma (EC) that can affect any part of the esophagus, but is usually located in the upper or middle third. "In a gene enrichment and meta-analytic study, NDC1 was reported as one of the critical genes in addition to NUP107 and NUP155 genes regulating esophageal squamous cell carcinoma (ESCC)." (PMID 34970494, 2021).
glioma (1 paper, 2022). A benign or malignant brain and spinal cord tumor that arises from glial cells (astrocytes, oligodendrocytes, ependymal cells). "BMP2 and HEY2 were identified as protective factors (HR < 1), and NUP107, DRAM1, F2R, PXDN, RNF19A, and SCG5 were identified as risk factors for glioma (HR > 1)." (PMID 36245971, 2022). "But we still failed to verify the significant differential relative mRNA expression of BMP2 and NUP107 between gliomas and adjacent normal tissues." (PMID 36245971, 2022).
myocardial infarction (1 paper, 2019). Gross necrosis of the myocardium, as a result of interruption of the blood supply to the area, as in coronary thrombosis. "Data mining 22 and our results indicate that the members of Nup107 complex are greatly increased after myocardial infarction, suggesting the dynamical regulation of Nup107 complex in response to cardiac injury." (PMID 30506890, 2019).
oligodendroglioma (1 paper, 2022). A well-differentiated (WHO grade II), diffusely infiltrating neuroglial tumor, typically located in the cerebral hemispheres. "As an essential component of the nuclear pore complex, Nucleoporin 107 (NUP107) may contribute to the regulation of cell fate in aged and transformed cells by modulating nuclear trafficking of signal based on undifferentiated oligodendroglioma cells in vitro." (PMID 36245971, 2022).
osteosarcoma (1 paper, 2020). A usually aggressive malignant bone-forming mesenchymal neoplasm, predominantly affecting adolescents and young adults. "The images were acquired in wild-type U-2 human osteosarcoma (OS) cells expressing Nup107-SNAP, which were fluorescently labeled with the organic dye Alexa-647 and induced to photoswitch by modifying the imaging buffer." (PMID 33290385, 2020).
pancreatic ductal adenocarcinoma (1 paper, 2022). An infiltrating adenocarcinoma that arises from the epithelial cells of the pancreas. "Based on the bioinformatics analysis, NUP107 is identified as a pivotal gene involved in pancreatic ductal adenocarcinoma (PDAC), which may be a molecular marker for the early diagnosis." (PMID 35416526, 2022).
sterility (1 paper, 2022). "Given the tissue-specific importance of Nup107 for ovarian development, and female-specific sterility in knockdown animals,29,30NUP107 seems to be a strong candidate to possibly explain the POI in our patients, requiring further study." (PMID 34906446, 2022).
thyroid cancer (1 paper, 2023). "We analyzed NUP107 mRNA levels across 33 human cancers and the corresponding normal tissues, and found that NUP107 was significantly elevated in 26 cancer types, such as liver, bladder, colorectal, breast, prostate, lung, and thyroid cancers." (PMID 36952458, 2023).
type 2 diabetes mellitus (1 paper, 2023). A type of diabetes mellitus that is characterized by insulin resistance or desensitization and increased blood glucose levels. "We also found changes in the expression of nucleoporin genes such as NDC1, NUP35, NUP58, NUP107, NUP160, and POM121C in pancreatic beta cells of patients with type 2 diabetes mellitus." (PMID 37569434, 2023).
cancer (11 papers, 2012 to 2024). A tumor composed of atypical neoplastic, often pleomorphic cells that invade other tissues. "NUP107 was highly expressed among 26 human cancers including HCC, and associated with advanced HCC staging and worse prognosis." (PMID 36952458, 2023). "NUP107 was highly expressed in 26 human cancers including HCC, and was associated with advanced HCC staging and worse prognosis." (PMID 36952458, 2023). "We also analyzed the genome and copy number of NUP107 in two HCC datasets in the cBioPortal for Cancer Genomics website (INSERM, Nat Genet 2015, TCGA, Firehose Legacy), and found that the frequency of NUP107 gene amplification and splice mutation was 1.3%." (PMID 36952458, 2023). "Previously, it was reported that NUP107 proteins are overexpressed in many types of cancers, including breast, prostate, colon, etc.." (PMID 30380781, 2018). "Recently, NUP107 was reported to participate in the progression of several cancers." (PMID 35416526, 2022). "Subsequently, to probe the effect of NUP107 and C8orf76 in cancer patients’ survival, we divided all samples into high-expression and low-expression groups and compared the OS rate of the other 32 cancer types." (PMID 35416526, 2022). "The result revealed that NUP107 was significantly differentially expressed in 15 cancer types." (PMID 35416526, 2022). "More interestingly, NUP107 and C8orf76 might play a significant role in the TIME of GAC and could be a potential biomarker for cancer prognosis." (PMID 35416526, 2022).
infection (6 papers, 2018 to 2025). The state of being infected such as from the introduction of a foreign agent such as serum, vaccine, antigenic substance or organism. "On MQTL10P.1, orthologue of NUP107 gene was found which is required for the plant’s response to infection by virulent pseudomonads." (PMID 36192697, 2022). "There were, however, a number of differences in Nup requirements for HIV-1WT infection in RANBP2∆Cyp cells, including a dramatic increase in sensitivity to NUP155 knockdown, and decreased sensitivity to NUP107, NUP93, and RANBP2 depletion." (PMID 39853118, 2025). "We observed that NUP98 protein levels were decreased both in SupT1 and HEK293T cell types upon HIV-1 NL4.3 infection by 4.7- and 1.5-fold, respectively (respectively), whereas the protein levels of other NUPs such as NUP62, NUP155, NUP133, NUP107, and NUP85 remained unaffected." (PMID 38449868, 2024). "Our data showed that Ad‐Nup107 infection did not affect the production of either nascent or mature Scn5a mRNA in NRVMs, compared with the Ad‐GFP‐treated cells." (PMID 30506890, 2019). "The CsA dependence of HIV-1A92E infection in HeLa cells was exaggerated by some Nup knockdowns (e.g. NUP93, NUP205, NUP54, NUP153) while other knockdowns reduced or eliminated the enhancing effects of CsA (e.g. NUP98, NUP107, NUP155)." (PMID 30084827, 2018). "Thus, our analysis further validated the 3CLpro cleavage of NUP107 and PAICS during infection and identified four new high-confidence new candidate 3CLpro substrates in a dataset that included samples that were not enriched for neo-termini, thus validating our approach." (PMID 37240067, 2023).
tumor (2 papers, 2023 to 2024). "NUP107 was significantly upregulated in most human tumor tissues, including HCC, compared to the corresponding normal tissues, and correlated to more advanced HCC staging and worse prognosis." (PMID 36952458, 2023). "The CXCR4‐CXCL12 axis attracts Tregs and pDCs to enhance tumor growth, which may be one of the mechanisms through which NUP107 promotes HCC growth." (PMID 36952458, 2023). "We found that NUP107 was positively correlated with chemokines such as CCL28 and CXCL8 (r = 0.310, p < 0.001), and the chemokine receptors CCR8 and CXCR4 suggesting that NUP107 overexpression may recruit immune cells to the tumor tissues." (PMID 36952458, 2023). "Thus, NUP107 may influence the progression of HCC by regulating the tumor immune microenvironment." (PMID 36952458, 2023).
cardiac diseases (1 paper, 2019). "In summary, our findings clarify for the first time the mechanism by which Nup107 regulates cardiac electrical activity through controlling posttranscriptional transportation, and has provided valuable insight into the molecular modulator in cardiac diseases." (PMID 30506890, 2019).
NUP107 also shares sentences with these, for which no sentence is quoted: colon cancer (2 papers); alcohol dependence (1); ciliopathies (1); cystic kidney disease (1); Galloway-Mowat syndrome (1); glomerulopathy (1); hepatitis B virus infection (1); kidney disease (1); liver cancer (1); lung carcinoma (1); metastatic tumours (1); nephritis (1); Nephropathy (1); neurological diseases (1); ovarian insufficiency (1); paraganglioma (1); pheochromocytoma (1); Premature ovarian insufficiency (1); renal clear cell carcinoma (1); steroid-resistant nephrotic syndrome (1); uterine corpus endometrioid carcinoma (1).